RNU6-884P (RNA, U6 small nuclear 884, pseudogene)
Gene: Small nuclear RNA gene on chromosome 1 (151,022,746 to 151,022,852, reverse strand). Ensembl gene ENSG00000200759.
Homologues: Orthologues: chimpanzee U6 (98% identical), macaque U6 (88% identical), rabbit U6 (85% identical), dog U6 (80% identical), mouse Gm25716 (72% identical). Paralogues in human: RNU6-43P (88% identical), RNU6-1243P (87% identical), RNU6-727P (87% identical), RNU6-1091P (86% identical), RNU6-24P (86% identical), RNU6-571P (86% identical), RNU6-944P (86% identical), RNU6-1094P (85% identical), RNU6-140P (85% identical), RNU6-199P (85% identical), RNU6-238P (85% identical), RNU6-454P (85% identical), and 1285 more.